DKK3 (dickkopf Wnt signaling pathway inhibitor 3)
Diseases named in the same sentence as DKK3 in open-access papers (continued):
Sharing a sentence is not in itself a finding about the gene and the disease.
breast cancer (continued). "An association between loss of DKK3 expression and EMT in breast cancer has already been described by other groups." (PMID 27467270, 2016). "Functionally, DKK3 re-expression in human breast cancer cell lines led to suppression of cell growth possibly mediated by up-regulation of apoptosis in basal-like but not in luminal-like breast cancer cell lines." (PMID 27467270, 2016). "Analyzing a large in silico dataset comprising 3,554 cases showed that low DKK3 mRNA expression was significantly associated with reduced recurrence free survival (RFS) of luminal and basal-like breast cancer cases." (PMID 27467270, 2016). "In contrast to moderate, predominantly cytoplasmic DKK3 protein expression in the normal breast epithelium (median IRS = 4), only weak DKK3 protein staining was observed in epithelial breast cancer cells." (PMID 27467270, 2016). "have reported that DKK3 inhibited the activation of β‐catenin and its downstream genes by abrogating its nuclear translocalization in breast cancer." (PMID 26395974, 2015). "The AXIN2 rs3923087, DKK3 rs6485350 and the SFRP3 rs7775 that was significantly associated with decreased risk of breast cancer in the overall study population also exhibited significant protection for the ER + as well as ER- group." (PMID 23516639, 2013). "DKK3 methylation was detected in 78% of breast tumour samples, whereas only rarely methylated in normal breast and surgical margin tissues, suggesting tumour-specific methylation of DKK3 in breast cancer." (PMID 23890219, 2013). "In this study, we demonstrated that DKK3 methylation was found in 80% of breast cancer cell lines and 78% of primary breast cancer tissues in Asian population." (PMID 23890219, 2013). "Promoter methylation of the DKK3/ITIH5 gene combination allowed significant discrimination of breast cancer sera from various control conditions." (PMID 23320751, 2013). "Except the SNP in β-catenin gene which was associated with increased risk of breast cancers, the other four SNPs in AXIN2, DKK3, SFRP3 and TCF7L2 genes were associated in a protective manner." (PMID 23516639, 2013). "We observed statistically significant association of SNPs in β-catenin (rs4135385), AXIN2 (rs3923087), DKK3 (rs6485350), SFRP3 (rs7775) and TCF7L2 (rs12255372) genes with breast cancer risk." (PMID 23516639, 2013). "Genetic variants in AXIN2, DKK3, SFRP3 and TCF7L2 were associated with reduced risk of breast cancer." (PMID 23516639, 2013). "Methylation of DKK3 was present in serum from two (1.5%) of 135 matched control subjects and 41 (29.7%) of 138 breast cancer patients (P < 0.0001)." (PMID 23320751, 2013). "We examined the expression and promoter methylation of DKK3 in 10 breast cancer cell lines, 96 primary breast tumours, 43 paired surgical margin tissues and 16 normal breast tissues." (PMID 23890219, 2013). "As JNK pathway plays an important role in non-canonical Wnt signalling, we further assessed the effect of DKK3 on JNK signalling in breast cancer cells." (PMID 23890219, 2013). "Genotypic analysis of individual locus showed statistically significant association of five SNPs located in β-catenin, AXIN2, DKK3, SFRP3 and TCF7L2 with breast cancers." (PMID 23516639, 2013). "We further demonstrated the ability of DKK3 to suppress cell growth and induce apoptosis in breast cancer, supporting that it does act as a TSG in line with the findings in another report." (PMID 23890219, 2013). "The effects of DKK3 on subcellular localization of β-catenin were performed in breast cancer cells with abundant level of endogenous β-catenin." (PMID 23890219, 2013). "This demonstrates that in spite of a statistical association between methylation of the two genes, there is still a large fraction of breast cancer patients with different DKK3/WIF1 methylation pattern." (PMID 19570204, 2009).
breast cancer (continued). "In the respective report, we have demonstrated that DKK3 methylation was present in 61.3% of breast cancer patients (92 of 150), whereas in 19 matching normal breast tissues only one sample (5.3%) revealed faint methylation signals." (PMID 19570204, 2009). "Although the Wnt antagonist genes WIF1 and DKK3 show a very similar frequency of promoter methylation in human breast cancer, only DKK3 methylation proves as a novel prognostic marker potentially useful in the clinical management of this disease." (PMID 19570204, 2009). "In breast carcinomas, WIF1 methylation was significantly associated with methylation of DKK3 (p = 0.009)." (PMID 19570204, 2009). "WIF1 and DKK3 promoter methylation were detected in 63.3% (95/150) and 61.3% (92/150) of breast carcinoma samples, respectively." (PMID 19570204, 2009). "WIF1 and DKK3 promoter methylation were assessed by methylation-specific PCR with bisulfite-converted DNA from 19 normal breast tissues and 150 primary breast carcinomas." (PMID 19570204, 2009). "In summary, we demonstrate for the first time that the Wnt antagonist gene DKK3 is a frequent target of epigenetic inactivation in human breast cancer, leading to downregulation of DKK3 mRNA and DKK3 protein expression in tumourous tissues." (PMID 18826564, 2008). "We have shown that a large proportion (61%) of breast cancer patients have DKK3 promoter methylation in the carcinoma tissue, leading to a functional inactivation of the tumour-protective protein." (PMID 18826564, 2008). "The induction of DKK3 mRNA transcription after the treatment as determined by realtime PCR ranged from 4.7-fold to 29-fold higher than in originally methylated breast cancer cells." (PMID 18826564, 2008). "Our results demonstrate for the first time that DKK3 expression is frequently downregulated in human breast cancer as a consequence of aberrant DNA methylation within the DKK3 gene promoter." (PMID 18826564, 2008). "This study shows that the putative Wnt antagonist DKK3 is frequently downregulated in human breast cancer due to promoter methylation, whereas it is abundantly expressed and unmethylated in normal breast cell epithelium." (PMID 18826564, 2008). "DKK3 mRNA expression and consequently DKK3 protein expression become frequently downregulated during human breast cancer development due to aberrant methylation of the DKK3 promoter." (PMID 18826564, 2008). "In summary, our data demonstrate for the first time that promoter methylation-mediated downregulation of DKK3 expression is a frequent and tumour-related epigenetic alteration in the development of human breast cancer." (PMID 18826564, 2008). "More recently, a breast cancer xenotransplantation model demonstrated that a single adenoviral-mediated intra-tumoural injection of a DKK3 expression vector efficiently discontinued tumour growth, with the induction of apoptosis in these cells." (PMID 18826564, 2008). "The most recent findings from a breast cancer study revealed that DKK3 not only attenuates tumour growth in a xenotransplantation mouse model, it also re-sensitised multidrug-resistant MCF7/ADR cells to doxorubicin treatment in a JNK-c-Jun dependent manner." (PMID 18826564, 2008). "DKK3 mRNA was downregulated in 71% (five of seven) of breast cancer cell lines and in 68% of primary breast carcinomas (27 of 40) compared with benign cell lines and normal breast tissues, respectively." (PMID 18826564, 2008). "In vitro DNA demethylation was performed by incubating breast cell lines with 5-aza-2'-deoxycytidine and trichostatin A. DKK3 protein expression was analysed by immunohistochemistry in breast carcinomas (n = 16) and normal breast tissues (n = 8)." (PMID 18826564, 2008). "Of the breast carcinomas, 61% (92 of 150) revealed a methylated DKK3 promoter, whereas 39% (58 of 150) retained an unmethylated promoter." (PMID 18826564, 2008).
breast cancer (continued). "In primary breast carcinomas, DKK3 mRNA expression was downregulated in 68% of invasive tumours with significant association with methylation of the DKK3 gene promoter (p < 0.001)." (PMID 18826564, 2008). "For all breast carcinoma samples analysed for DKK3 mRNA expression (n = 59) we determined the DKK3 promoter methylation status at the same time." (PMID 18826564, 2008). "The total frequency of DKK3 methylation was 61% in breast carcinomas, whereas corresponding normal breast tissues were unaffected by this epimutation." (PMID 18826564, 2008). "Dickkopf-3 (DKK3) is considered a tumor suppressor as it is often deleted in cancers and is frequently downregulated owing to epigenetic inactivation in cervical, lung, prostate, bladder, gallbladder, and breast cancers." (PMID 35205672, 2022). "Furthermore, DKK1 and DKK3 promoter hypermethylation have been documented in many primary breast cancer tumours." (PMID 33462997, 2021). "In a separate study, the rate of Dkk3 promoter methylation was higher in breast cancer than in normal tissue and was independently associated with adverse prognosis." (PMID 33425757, 2020). "However, in other types of cancer, such as gastric cancer, breast cancer and ovarian cancer, upregulated DKK3 mRNA expression has been found." (PMID 31423109, 2019). "ITIH5 was included on basis of previous work, where we showed that a panel of ITIH5 and DKK3 could detect breast cancer with 41% sensitivity." (PMID 31741713, 2019). "Interestingly, DKK3 re-expression in mesenchymal-like MDA-MB-436 breast cancer cells resulted in a modified cell morphology." (PMID 27467270, 2016). "In conclusion, our findings provide for the first time evidence that DKK3 might have a subtype-specific function in human breast cancer." (PMID 27467270, 2016). "However, as breast cancer is a heterogeneous disease one goal of this study was to perform a comprehensive subtype-specific DKK3 expression analyses in human breast cancer for the first time." (PMID 27467270, 2016). "Interestingly, most abundant reduction of DKK3 expression was detected in the highly aggressive basal breast cancer subtype." (PMID 27467270, 2016). "Moreover, we demonstrated strong growth suppressive effects mediated by DKK3 in basal-like breast cancer cells indicating a prominent role for DKK3 especially in the tumorigenesis of this clinically highly relevant breast cancer subtype." (PMID 27467270, 2016). "Hence, we provide evidence that down-regulation of DKK3 especially promotes tumorigenesis of the aggressive basal breast cancer subtype." (PMID 27467270, 2016). "This indicates a role for DKK3 in tumor growth regulation most notably in basal breast cancers." (PMID 27467270, 2016). "Therefore, we initiated a study analyzing the subtype-specific DKK3 expression pattern as well as its prognostic and functional impact with respect to breast cancer subtypes." (PMID 27467270, 2016). "Previously, other studies could already demonstrate that DKK3 is able to suppress cell growth and to induce apoptosis in human breast cancer cell lines, indicating a tumor suppressive function for DKK3." (PMID 27467270, 2016). "However, the current study is the first to analyze the impact of DKK3 mRNA expression on breast cancer patient survival." (PMID 27467270, 2016). "DKK3 has been claimed to be downregulated in a broad range of cancers, such as non-small cell lung cancer, breast cancer, gastric cancer, and melanoma, and this reduced expression was correlated with lower survival rates of patients from the respective cancer types." (PMID 26734010, 2015). "In this study, we assessed the expression and promoter methylation of DKK3 in breast cancer." (PMID 23890219, 2013). "In the present study, we addressed the question to whether promoter methylation of two Wnt antagonist genes (WIF1 and DKK3), that were previously reported as hypermethylated in breast cancer, provides prognostically relevant information in this tumor entity." (PMID 19570204, 2009).
breast cancer (continued). "In conclusion, our results demonstrate that determination of the DKK3 methylation status may provide valuable information to aid prognostication in the clinical management of breast cancer patients." (PMID 19570204, 2009). "We have recently reported of frequent DKK3 promoter methylation in human breast cancer." (PMID 19570204, 2009). "Therefore downregulation of DKK3 mRNA in breast cancer is considered to affect about 70% of patients." (PMID 18826564, 2008). "Our study is the first to analyse DKK3 gene regulation in human breast cancer." (PMID 18826564, 2008). "To address the question of whether DKK3 promoter methylation occurs in primary breast carcinomas, we analysed 150 mammary tumour samples by MSP." (PMID 18826564, 2008). "Thus, we were able to directly compare DKK3 methylation and mRNA expression in primary human breast carcinomas." (PMID 18826564, 2008). "DKK3 mRNA expression and DKK3 promoter methylation were determined by RT-PCR, realtime PCR and methylation-specific PCR in breast cell lines (n = 9), normal breast tissues (n = 19) and primary breast carcinomas (n = 150), respectively." (PMID 18826564, 2008). "Of the breast carcinomas, four of 16 (25%) revealed abundant DKK3 protein expression (IRS = 9 to 12) in contrast to seven of 16 tumours (44%), which showed partial loss (IRS = 4 to 8), and five of 16 tumours (31%) with substantial loss of DKK3 protein (IRS = 0 to 3)." (PMID 18826564, 2008). "DKK3 is reported as overexpressed in esophageal adenocarcinoma, head and neck squamous cell carcinoma, and hepatoblastoma; whereas studies have reported its downregulated in pancreatic cancer, clear cell renal cell carcinoma, gastric cancer, basal subtype of breast cancer, and melanoma." (PMID 31737564, 2019). "Likewise, decrease of DKK3 expression in human breast cancer was described before." (PMID 27467270, 2016). "Silencing of DKK3 by promoter methylation in breast cancer indicated that it may function as a TSG." (PMID 23890219, 2013). "Collectively, our results demonstrate that DKK3 functions as a tumour suppressor inhibiting Wnt/β-catenin signalling in breast carcinogenesis, and raises the possibility of DKK3 methylation as a potential tumour marker and future therapeutic target for breast cancer." (PMID 23890219, 2013). "Although WIF1 is similarly frequent hypermethylated like the Wnt antagonist gene DKK3, and neither gene methylation is associated with relevant clinicopathological factors, DKK3 methylation is an independent prognostic factor in breast cancer patient survival, whereas WIF1 methylation is not." (PMID 19570204, 2009). "Therefore, we conclude that a potential gene therapeutic treatment with DKK3 might be of benefit for a large target population of breast cancer patients." (PMID 18826564, 2008). "PRMT5 regulates breast cancer cell growth through epigenetic silencing of DKK1 and DKK3, which are WNT/β-CATENIN pathway antagonists, thus resulting in up-regulation of WNT/β-CATENIN proliferative signaling." (PMID 37924099, 2023). "Collectively, these results show that PRMT5 controls breast cancer cell growth through epigenetic silencing of WNT/β‐CATENIN pathway antagonists, DKK1 and DKK3, resulting in up‐regulation of WNT/β‐CATENIN proliferative signalling." (PMID 33462997, 2021). "The sensitivity and specificity achieved using ITIH5, DKK3 and RASSF1A promoter methylation to distinguish between women with breast cancer and healthy controls was 67 and 69%, respectively, with the 95% confidence interval for the AUC being [0.63, 0.76]." (PMID 29301500, 2018). "Several Wnt/β-catenin antagonists were epigenetically repressed in breast cancer, including WIF1, SFRP1, SFRP2, SFRP5, DKK1, and DKK3." (PMID 28467796, 2017).
breast cancer (continued). "Furthermore, it could be shown that DKK3 affects tumor cell growth due to induction of apoptosis in mammary carcinomas and several other cancer types and might be involved in the inhibition of epithelial-to-mesenchymal transition (EMT), indicating a role for DKK3 as a tumor suppressor gene." (PMID 27467270, 2016). "Our next goal is to discover and characterize more potential biomarkers for early breast cancer detection with a quality comparable to that of ITIH5 and DKK3 promoter methylation." (PMID 23320751, 2013). "We initially assessed promoter methylation of SFRP1, SFRP2, SFRP5, ITIH5, DKK3, and WIF1 in 112 paired breast cancer tissue and serum samples by using qualitative MSP." (PMID 23320751, 2013). "In the present study, seven potential breast cancer marker candidates (SFRP1, SFRP2, SFRP5, WIF1, DKK3, ITIH5, and RASSF1A) were studied with regard to early breast cancer detection in serum." (PMID 23320751, 2013). "The potential biomarkers DKK3 and ITIH5 seem to be more breast cancer specific (94% to 99%) but less sensitive (14% to 33%) in both the test and the validation sets." (PMID 23320751, 2013). "In summary, the three-marker panel with ITIH5, DKK3, and RASSF1A exhibits significantly increased levels of methylation in serum cfDNA from breast cancer patients compared with both age-matched healthy women and women with a benign breast disease." (PMID 23320751, 2013). "In five further breast cancer cell lines (BT20, MCF7, MDA-MB231, T47D and ZR75-1) DKK3 expression was substantially reduced." (PMID 18826564, 2008). "For example, DKK3 promoter methylation was found in 78% of patients with primary breast cancer, and these patients had a poorer prognosis and higher metastasis rates than patients without DKK3 methylation." (PMID 36810560, 2023). "In addition, we found that miR-378 expression was negatively correlated with DKK3 and NUMB expression in breast cancer based on the TCGA database (n = 470) (p < 0.001)." (PMID 33823894, 2021). "Furthermore, at 48 h after rescuing DKK3 or NUMB expression, sphere formation assays and western blot analysis showed that the effect of chemotherapy-elicited exosomes on breast cancer stemness was rescued (p < 0.0001)." (PMID 33823894, 2021). "Furthermore, after transfection with miR-378 mimics and the DKK3 or NUMB overexpression plasmids, western blot analysis showed that the effect of miR-378a-3p and miR-378d on breast cancer stemness was rescued." (PMID 33823894, 2021). "Finally, we provide a schematic representation of the biological role of the trans-cellular signaling pathway involving EZH2, STAT3, exo-miR-378a-3p, exo-miR-378d, DKK3 and NUMB in the regulation of breast cancer chemoresistance." (PMID 33823894, 2021). "To investigate DKK3 in tractable models, we isolated CAFs from murine mammary carcinomas and human breast, colon and ovarian cancers, as well as normal tissue counterparts (NFs)." (PMID 30631061, 2019). "Ectopic expression of DKK3 significantly suppressed cell growth solely in basal-like but not in luminal-like breast cancer cell lines (MDA-MB-436, P < 0.01 and MDA-MB-231, P < 0.05)." (PMID 27467270, 2016). "Further support was obtained by the positive correlation between low DKK3 mRNA expression and negative hormone receptor status using our own as well as the TCGA breast cancer data set." (PMID 27467270, 2016). "DKK3 re-expression resulted in cell growth suppression possibly mediated by up-regulation of apoptosis in the basal-like but not in the luminal-like breast cancer models." (PMID 27467270, 2016). "However, recently DKK3 is shown to inhibit canonical WNT signaling specifically in lung and breast cancer cells." (PMID 23667645, 2013). "We hypothesize that DKK3 and ITIH5 may be valuable biomarkers for the blood-based detection of breast cancer in patients with dense breast tissue because of their high specificity in the control specimens." (PMID 23320751, 2013).